HIF1A (hypoxia inducible factor 1 subunit alpha)
Diseases named in the same sentence as HIF1A in open-access papers (continued):
Sharing a sentence is not in itself a finding about the gene and the disease.
cancer (continued). "Several known cancer-associated genes are located on 14q, including CHD8, FOXA1, HIF1A, and DICER1, encoding proteins involved in DNA damage/response, hypoxia response, and miRNA processing, respectively." (PMID 34205964, 2021). "Thereafter, in situ post-radiation monitoring (one day, three days, seven days post-irradiation) of the 3D cell cultures took place via quantification of (i) live/dead and apoptotic profiles and (ii) ECM (collagen-I) and HIF-1a secretion by the cancer cells." (PMID 34885188, 2021). "HIF-1α triggers expression of various oncogenes, conferring resistance to chemotherapy and radiotherapy and inducing cancer progression." (PMID 34200349, 2021). "Together, these findings highlighted that the HIFAL was essential for PKM2 to drive HIF-1α mediated transcription in cancer development." (PMID 33637716, 2021). "RON has been shown to be a downstream target of HIF1α in other cancers and as such, is a potential downstream or direct target of 2-ME2." (PMID 33673346, 2021). "LW6, an (aryloxyacetylamino)benzoic acid derivative, was recently identified to be an inhibitor of hypoxia-inducible factor-1α (HIF-1α), which is an attractive target for cancer therapeutics." (PMID 33921487, 2021). "NuF can inhibiting IL-6 and TGF-β trigger EMT that influences the HIF-1α activity for inhibiting cancer progression during Iressa therapy." (PMID 34064322, 2021). "During hypoxia, the hypoxia-inducible factor 1 (HIF-1)-α transcriptionally upregulates PKM2, which binds to HIF-1-α and stimulates the transcription of glycolytic genes that promote glucose metabolism in cancer cells." (PMID 34359752, 2021). "Accordingly, it has been shown that VEGF expression was significantly down-regulated when HIF-1α was knocked down in bone marrow stem cells and cancer cells, leading to poorly vascularized constructs." (PMID 34368116, 2021). "The HDAC inhibitor TSA has been demonstrated to decrease HIF-1α protein stability and cancer cell tolerance to hypoxia." (PMID 34540836, 2021). "Regarding lipid metabolism, several studies in cancer, including BC, have shown that HIF-1α increases the availability of fatty acids by regulating the action of fatty acid synthase (FAS), increasing fatty acid transport and reducing fatty acid oxidation." (PMID 34072826, 2021). "In conclusion, PCED1B-AS1 expression was upregulated in PDAC tissues and cells, and it participated in promoting the proliferation, invasion and EMT of cancer cells by modulating the miR-411-3p/HIF-1α axis." (PMID 34036383, 2021). "Cancer progression occurs in hypoxic conditions, and luteolin administration is of importance in reducing HIF-1α expression and disrupting hypoxia-mediated cancer progression." (PMID 33652780, 2021). "PFKFB3, also regulated by HIF-1α, was reported to be upregulated in multiple cancer types, where it was required for their survival and growth." (PMID 34683117, 2021). "In subsequent studies, it would be essential to test the involvement of Smurf2 in HIF-1α regulation in various cancer types especially including both VHL-sufficient and VHL-deficient cancers." (PMID 34611473, 2021). "At this level, the mode of action of BRT is reminiscent of that of the quassinoid brusatol, which is also an inhibitor of Nrf2 and c-Myc, which increases HIF-1α degradation to induce cell death of cancer cells." (PMID 34680439, 2021). "Cancer development and progression depend mainly on three factors—the presence of hypoxia (HIF-1a activation), inflammation (NF-kB activation), and ER-α." (PMID 34684168, 2021). "Hypoxia-Inducible Factor 1α (HIF-1α), which promotes cancer cell survival, is the main regulator of oxygen homeostasis." (PMID 34359734, 2021). "The resulting hypoxia stimulates the hypoxia-inducible factor1α (HIF-1α) pathway, priming cancer cells for survival against a variety of cellular death mechanisms induced by radio- or chemotherapy including autophagy, apoptosis, and DNA damage." (PMID 33513777, 2021).
cancer (continued). "HRGs such as hypoxic‐inducible factor 1α (HIF1A) can promote the expression of PD‐L1 in mouse models of cancer." (PMID 34250747, 2021). "Hypoxic cancer cells can upregulate C-C motif chemokine ligand 28 (CCL28) levels via HIF-1α, stimulating the recruitment of Tregs into the tumor microenvironment and allowing cancer cells to avoid immune surveillance." (PMID 34298879, 2021). "Deletion of HIF-1α has sensitized cancer cells to radiotherapy, and this suggests HIF-1α promotes radiation resistance in a cell autonomous manner." (PMID 34746010, 2021). "Melatonin, also known as N‐acetyl‐5‐methopxytryptamine, is produced naturally by the pineal gland and has anti‐angiogenic effects in cancer through its ability to modulate HIF‐1α activity." (PMID 33955074, 2021). "By cooperating with HIF-1α in up-regulating MMP9, PERK and HIF-1α also promote migration, helping cancer cells to leave unfavorable environments and escape from cytotoxic agents." (PMID 33423689, 2021). "This review article presents the effects of compounds derived from plants on HIF-1α in conjunction with their efficacy in cancer." (PMID 34575983, 2021). "In the context of cancer, most tumors have hypoxic regions and, in this case, HIF-1α is stabilized and triggers changes in glycolysis, nutrient uptake, waste handling, angiogenesis, apoptosis, and cell migration, which promote tumor survival and metastasis." (PMID 34072826, 2021). "Most importantly, we confirmed that OLFM4 contributes to cancer cell proliferation, and HIF-1α is involved in this process." (PMID 34912753, 2021). "VHL E3 ligases complex is essential for regulating the expression of HIF1α that contributes to various cancers development." (PMID 35006464, 2021). "Both HIF-1α and pAP-1 c-Jun proteins are key players in cancer cells resistance to anti-angiogenic therapies and activate distinct transcriptional programs that converge to coordinate ECM degradation and metastasis, via MMPs33,53." (PMID 34764332, 2021). "Our data sets and analyses thus provide a resource for advanced understanding of the role of HIF1A and its targets in cancer biology." (PMID 33654095, 2021). "HIF‐1α is a powerful transcriptional factor for cancer‐related genes, and it regulates energy metabolism, angiogenesis, apoptosis, and cell survival." (PMID 33773069, 2021). "HIF-1α inhibits cancer cell apoptosis by promoting the expression of VEGF, glucose transporter 1, and other anti-apoptotic agents." (PMID 33621198, 2021). "Hypoxia and HIF1α contribute to the malignant cancer progression phenotype across diverse cancer types." (PMID 34686682, 2021). "Researchers have summarized the molecular mechanisms participated in hypoxia-induced exosomes biogenesis and cargo loading (miRNAs, proteins, and lipids) in cancer cells, including HIF-1α, ceramides, RAB GTPases, ROCK, tetraspanins, oxidative stress." (PMID 33824273, 2021). "Several cancer-associated signaling pathways have been implicated in the activation of SOX4, including Wnt, TNF-α, TGF-β, and hypoxia/HIF-1α signaling." (PMID 33407675, 2021). "More importantly, nuclear PKM2 interacts with HIF1α and β-catenin to regulate the expression of glycolytic enzymes and initiate the Warburg effect in cancer cells." (PMID 34887764, 2021). "Nox4 binds to p22phox and contributes to cancer development and progression via ROS release and HIF-1α in cancer cells." (PMID 34942984, 2021). "Previously, it has been shown that P4HA1 stabilizes hypoxia-inducible factor 1α (HIF1α) by modulating the levels of its glycolytic substrates, α-ketoglutarate, and succinate, thus mediating cellular transformation of cancer cells." (PMID 34337075, 2021).
cancer (continued). "PFKFB3 not only contributes to the proliferation, metastasis, and angiogenesis of cancer but also induces the resistance of liver cancer cells to sorafenib through the PFKFB3/HIF-1A positive feedback loop." (PMID 34540667, 2021). "MYC and HIF1α are critical in human cancer pathogenesis through regulation of metabolism, angiogenesis, cell proliferation and apoptosis, and self-renewal of cancer stem cells." (PMID 33572152, 2021). "Exposure to arsenic can increase the expression of miRNA-21 (a well-known cancer-related miRNA) through overexpression of HIF-1α induced by arsenic-mediated activation of the PI3K/AKT pathway." (PMID 34659330, 2021). "As HIF1α is well-established to facilitate oncogenesis in a variety of cancers, the HACE1-RAC1 axis provides an attractive potential target for therapeutic intervention." (PMID 33603169, 2021). "Geldanamycin inhibits the UPR pathway's chaperones, reduces the HIF1-α stabilization, and stimulates the hypoxic carcinoma death." (PMID 34717757, 2021). "Hypoxia-inducible factor 1 alpha (HIF-1α) is a key regulator of cellular response to hypoxia, which can be detected in many carcinomas, including OC." (PMID 34659640, 2021). "And also, 2-HG affects the metabolism of complex IV/V resulting in deregulation of the mitochondrial energetics, stabilization of HIF-1α, and carcinoma progression." (PMID 34717757, 2021). "HIF-1α has been reported to play an important role in the metabolism and metastasis of cancer cells." (PMID 32312328, 2020). "EYA1 was reported to regulate VEGF-A during angiogenesis through HIF-1α signaling pathway in a cancer model, which is consistent with our findings in the PA animal model." (PMID 32456711, 2020). "Studies have shown that HIF-1α is frequently aberrantly expressed in human cancer, and its expression level is tightly regulated by multiple factors at the transcriptional or post-transcriptional level." (PMID 32467667, 2020). "HIF-1α also plays a role in the modulation of PD-1/PD-L1, and therefore it provokes cancer resistance to RT and immunotherapy." (PMID 32872195, 2020). "It has been shown in various types of cancer cell lines that ROS can activate HIF-1α, which induced the expression of pluripotency factors." (PMID 32664372, 2020). "Previous studies have demonstrated that PH4B can induce malignant tumor cell proliferation, invasion and metastasis by regulating hypoxia inducible factor-1α (HIF-1α) expression and the MAPK signaling pathway." (PMID 32903592, 2020). "The HIF1α induced TKT expression in the resistant cells assist in increased pyrimidine synthesis that protects the cancer cells from gemcitabine-induced cytotoxicity." (PMID 32408513, 2020). "Vit.C has gained importance in the treatment of cancer due to its ability to modulate the redox status of the cell and influence epigenetic modifications and significant roles in HIF1α signaling." (PMID 31947879, 2020). "The tumorigenic effect caused by defective HF is, in part, attributed to the abnormal accumulation of fumarate, resulting in the inhibition of PHDs in the cytosol and thus, stabilization and activation of HIF1α, which plays a major role in cancer metabolism." (PMID 32764295, 2020). "Expression of PFKFB3 is not typical of liver tissue; however, this isoform is also known as inducible PFKFB, as it has been observed to be expressed in response to hypoxic conditions of cancer cells by hypoxia inducible factor 1-alpha (HIF1α)." (PMID 33083755, 2020). "In fact, HIF-1α activates the Warburg effect in cancer cells, which induces the release of lactate and protons in the bone microenvironment, which, in turn, signal to nociceptive terminals in the bone, causing pain." (PMID 32527062, 2020). "HIF-1α is involved in the adaptive response under hypoxic conditions and in the regulation of many pivotal pathways in cancer." (PMID 32045997, 2020).
cancer (continued). "During the early stages of cancer development, neoplastic tissue (excluding typical angiogenic phenotypes) remains mostly avascular after which HIF-1α-dependent release of VEGF is a key process promoting neovascularization." (PMID 32488850, 2020). "HepG2 and Hep3B xenograft models showed varying expression levels of GLUT1 and Ki67 depending on heterogeneous CAIX expression, a hypoxia-inducible metal-enzyme that promotes cancer cell survival and invasion via HIF1α activation." (PMID 32001727, 2020). "Although the mechanism of this process is not known, it has been suggested that hypoxia-inducible factor-1 alpha (HIF-1α) plays an important role in cancer cell metabolism." (PMID 31933109, 2020). "This ‘moonlighting’ activity has been demonstrated in macrophages, T cells and cancer cells where PKM2 supports the function of transcription factors including HIF1α and STATs." (PMID 32812866, 2020). "In cancer cells, other notable regulators of cellular iron metabolism include hypoxia-inducible factor 1α (HIF1α), the proto-oncogene MYC, and nuclear factor erythroid 2-related factor 2 (NRF2)." (PMID 33287315, 2020). "These specific effects in the TNBC cells were linked to DHA-mediated decreases in hypoxia-inducible factor 1 (HIF1)α, a key regulator of glycolytic metabolism and the Warburg effect in cancer cells." (PMID 33123546, 2020). "The results revealed that HIF1α was higher expressed in cancer tissues than in the paired normal lung tissues of NSCLC patients." (PMID 32878637, 2020). "CLDN6 has a potential role in the diagnosis and prognosis of cancers involving deregulated HIF-1α, and subsequently HIF-1α/SENP1-blocked therapies." (PMID 32093760, 2020). "Resveratrol improves mitochondrial biogenesis, fusion and respiration by HIF-1α down-regulation to stimulate cell cycle arrest in cancer cells." (PMID 32163546, 2020). "By doing so, HIF-1α-dependent alteration of lipid metabolism enables cancer cells to promote survival and growth." (PMID 33128030, 2020). "HIF1α is an important enzyme for metabolic adjustment during hypoxia and is involved in cancer cell survival, angiogenesis, and metastasis." (PMID 32318579, 2020). "Hypoxia-inducible factor-1 alpha (HIF-1α) is a transcription factor essential for cancer cell survival." (PMID 33128030, 2020). "Previous studies have identified that HIF1α directly down-regulates ER expression levels in cancer lines." (PMID 32639950, 2020). "Upregulation of HIF-1α expression is a common phenomenon in metastasis or aggressive phenotypes in many cancers such as lung, prostate, breast and pancreas carcinomas." (PMID 33097763, 2020). "Suggesting that by mediating the stabilization and activation of HIF-1α, OGT regulates HIF-1α target genes and functions in angiogenesis, as well as cancer metastasis." (PMID 33194731, 2020). "Studies have shown that pathways such as PI3K/AKT/mTOR and HIF-1α are central regulators of glycolysis, cancer metabolism, and cancer cell proliferation." (PMID 32076440, 2020). "OX-A administration correlated with the inhibition of cancer-related glycolysis via Sirtuin-3 mediated destabilisation of HIF-1α controlling expression of glucose degradation enzymes." (PMID 32843908, 2020). "Two miRNAs, miR-33a and miR-448, directly targeted HIF-1α to inhibit glycolysis and promote radiosensitivity of cancer cells." (PMID 32585857, 2020). "The analysis of 42 cancer tissues revealed a correlation of HIF-1α and miRNA-142 expression with disease stage and a correlation of miRNA-142 expression with lymphatic metastasis." (PMID 33113836, 2020). "The role of NFкB regulated pathways in maintaining and promoting hypoxia, inflammation and stemness in cancer cells has been an area of significant scientific interest and many NFкB/HIF-1α inhibitors are under clinical cancer trials." (PMID 31992226, 2020). "HIF-1α confers resistance on cancer cells due to glycolytic inhibitor 2-deoxyglucose, as well as biguanides such as metformin." (PMID 32354000, 2020).
cancer (continued). "HIF1α also activates the one-carbon (folate) pathway to protect cancer stem cells from increased oxidative stress by increasing NADPH (and glutathione) production." (PMID 32620753, 2020). "It has been shown that 1,25(OH)2D reduces the expression of the HIF-1α subunit and of the vascular endothelial growth factor and inhibits cancer cell proliferation under hypoxic conditions." (PMID 32024052, 2020). "HIF1 is a transcription factor found in many types of cancers and is composed of HIF-1α and HIF-1β subunits." (PMID 33182353, 2020). "An HIF-1α/Zeb1 signaling axis initiated by hypoxia has been described in several types of cancer cells." (PMID 32640738, 2020). "After 24-h treatment, the expression of nickel-induced ANGPTL4 and HIF-1α was significantly suppressed by metformin in both lung epithelial cells and cancer cells." (PMID 31963541, 2020). "An increase in the expression level of HIF-1α is revealed in several cancers which is a contributory factor for drug resistance and higher mortality." (PMID 33195038, 2020). "Hsa_circ_0014130 (circPIP5K1A), which is overexpressed in non-small cell lung cancer, facilitates cancer proliferation and metastasis by sponging miR-600, which interacts with the 3′ untranslated region of HIF-1α." (PMID 32518520, 2020). "For instance, lysine residue 532 (Lys-532) and lysine residue 709 (Lys-709) of HIF-1α protein can be acetylated in cancer cells." (PMID 33109235, 2020). "Silencing HIF1α decreased the expression of Oct4, Sox2 and Nanog, the central stemness genes in cancer cells." (PMID 32226544, 2020). "As a result of these diverse functions of its downstream genes, HIF-1α has been widely recognized as a target for cancer therapy." (PMID 32093760, 2020). "HIF-1α as the communicator between cancer cells and stromal cells exerts more influence than HIF-2α because the number of cancer cells dependent on HIF-1α was double that in cells dependent on HIF-2α in terms of viability." (PMID 32847073, 2020). "The elevated expression of glycolytic enzymes in cancers has been shown to rely on the increased stability of hypoxia inducible factor 1 α (Hif1α), which is the master transcriptional regulator of glycolysis." (PMID 31947613, 2020). "Conversely, 28 of cancer-related genes were downregulated by shNrf1, of which 6 genes (i.e., HIF1A, STAT5B, IGF1R, TGFBR1, ATRN, and FZD6) were upregulated by Nrf1α−/− to varying extents." (PMID 32273945, 2020). "Except for the HIF-1α/PPAR-γ/PKM2 axis investigated in the present study, the PKM2 isoform, PKM1, is also reported to increase glycolysis through autophagy and cause cancer chemoresistance." (PMID 32000827, 2020). "As induction of HIF-1α is known to deteriorate the state of cancer and EMT process is one of the hallmarks of metastasis in cancer, our findings uncover the role of neddylation between HIF-1α and ZEB1." (PMID 33097763, 2020). "Hypoxic cancer cells exhibit rapid VEGF expression, which is directly linked to hypoxia-induced factor HIF-1α." (PMID 33076322, 2020). "Specifically, together with hypoxia, ROS represent one of the major activators of HIF-1α, a transcription factor involved in the regulation of a wide plethora of cancer features such as invasion, metastasis, and angiogenesis." (PMID 32054075, 2020). "In this review, we briefly elucidate the reciprocal regulation between HIF-1α and ncRNAs, as well as their effect on cancer cell behaviors." (PMID 32014012, 2020). "It has been discovered that many drugs, such as aspirin and Tamoxifen, can block the growth of tumors by inhibiting the expression or activity of HIF-1α thereby providing new anti-cancer treatments." (PMID 32928258, 2020).